GZMB (granzyme B)
Diseases named in the same sentence as GZMB in open-access papers (continued):
Sharing a sentence is not in itself a finding about the gene and the disease.
tumor (continued). "For example, in the tumor-immune-enriched neighborhood, CD8+ T cells were enriched for Granzyme B, PD-1, and Ki-67, indicative of strong anti-tumor activity and terminal exhaustion while retaining their proliferative capacity." (PMID 41254766, 2025). "The combination of vaccine and ICI also promoted IFNγ, IL2, and granzyme B production in the tumor microenvironment, suggesting enhanced activation of antigen-specific T cells." (PMID 41012179, 2025). "RT alone promotes the expansion and differentiation of the TdLN derived PD-1+ TCF-1+ cells into TIM-3+ GZMB+ TCF-1- effector-like cells in the tumor with further enhancement after the addition of αPD-L1." (PMID 40229241, 2025). "Upon activation, γδT cells degranulate and release perforin, which forms pores in tumor cell membrane, allowing granzyme B to enter the target cell." (PMID 40226616, 2025). "CAR T cells at the tumor site were isolated and analyzed by flow cytometry; the data showed that IL15C-NKG2D-CAR T cells expressed higher levels of cytokines CD69, CD107, and GzmB at the tumor site." (PMID 40625735, 2025). "These effector T cells, along with NK cells, exert cytotoxic effects by releasing IFN-γ, granzyme B, and perforin, thereby contributing to tumor suppression." (PMID 40497988, 2025). "Accumulating evidence suggests that GZMB plays a highly complex and dualistic role in tumor progression." (PMID 41567188, 2025). "The iNKT cells also possess the capacity to exert direct cytotoxic effects on tumor cells via perforin, granzyme B, and FasL-mediated apoptosis." (PMID 40746558, 2025). "TNBCvax vaccination significantly increased CD8+ T cell infiltration and also upregulated the anti-tumor key effector molecules such as TNFα, IFNγ, and Granzyme B expression." (PMID 40969744, 2025). "Recently, nanotechnology has offered novel avenues for the precise delivery and functional regulation of GZMB, aiming to achieve specific targeting and efficient killing of tumor cells through this approach." (PMID 41567188, 2025). "Following PD-1/L1 blockade, the CD8+ PD-1+ TCF-1+ T cell subset expands and differentiates into a TIM-3+ GZMB+ subset which has the capacity for tumor killing." (PMID 40229241, 2025). "Perforin and granzyme B are also essential for NK cell-mediated tumor killing in the intrinsic pathway." (PMID 40076856, 2025). "This pattern suggests that myeloid-lineage cells are a major source of GZMB within the IBC tumor microenvironment." (PMID 41567210, 2025). "(E–H) Abundance of CD49b+ (E), NKp46+ (F), Granzyme B+ (G), and different development status (H) tumor-infiltrating NK cells." (PMID 40464376, 2025). "Our 12GM-DCs specifically expand antigen-specific T cells and enhance their secretion of IFN-γ and granzyme B, resulting in a higher proportion of tumor-killing T cells in the enriched culture." (PMID 41333469, 2025). "The ADCC effect mediates tumor cell death through triggered release of cytotoxic granules (e.g., perforin and granzyme B) and cytokines (e.g., IFN-γ and TNF-α)." (PMID 41293157, 2025). "It was observed that both the Tumor B and Tumor groups exhibited reduced levels of GZMB and IFN-γ, indicating that IL-6 can diminish the effector killing capacity of CD8+ T cells." (PMID 40040705, 2025). "Granzyme B is crucial for the cytotoxic activity of NK cells, which play an important role in the innate immune response against tumor." (PMID 40766321, 2025). "These cytokines are critical for effector T cell function: IFN-γ promotes antigen presentation and inhibits tumor angiogenesis, while GZMB mediates direct cytotoxicity against tumor cells." (PMID 41373467, 2025). "In contrast, Akkermansia muciniphila has been reported to activate CD8+ T lymphocytes and enhance T-cell effector functions by upregulating IFN-yγ and granzyme B (GZMB) in both in vitro and in vivo studies, indicating a tumor-suppressive role." (PMID 41375042, 2025).
tumor (continued). "Targeting Becn1 to inhibit autophagy significantly restores the levels of serine protease GZMB/granzyme B within target cells under hypoxic conditions and induces tumor regression in vivo by promoting NK cell-mediated tumor cell killing." (PMID 41246345, 2025). "Direct tumor toxicity, promoted by the recognition of CD1d-presented lipid antigens, is mediated by perforins, granzyme B, and over-expression of the Fas ligand." (PMID 40002679, 2025). "In 2010, research further substantiated the role of GZMB in enhancing tumor invasiveness through ECM remodeling." (PMID 41567188, 2025). "CD8+ T cells can lyse target cells and inhibit tumor growth by secreting cytotoxic granules such as perforin and granzyme B.25Activin A promoted the expression of cytotoxic components including perforin and granzyme B in CD8+ T cells." (PMID 39727149, 2025). "After 48 hours, PBMCs produced significantly higher levels of IFNγ and Granzyme B when co-cultured with tumor cells treated with MYC inhibitors." (PMID 40552293, 2025). "In CAR-T therapy, granzyme B cleaves GSDME in tumor cells, which triggers macrophage activation of caspase-1/GSDMD and leads to IL-1β/IL-6 release." (PMID 41291696, 2025). "Tc2 cells, which primarily produce type II cytokines, also express high levels of granzyme B and exhibit cytotoxicity comparable to Tc1 cells, making them significant in adoptive transfer anti-tumor therapies." (PMID 40458394, 2025). "We also probed for secreted perforin and granzyme B from CAR T cells after tumor encounter as a confirmatory measure for cytolytic degranulation." (PMID 39792660, 2025). "They directly induce tumor cell apoptosis by releasing perforin and granzyme B, while concurrently secreting cytokines such as interferon-gamma(IFN-γ) and TNF-α to inhibit tumor proliferation and activate macrophages." (PMID 40977714, 2025). "GZMB, a critical effector molecule in tumor immune responses, has attracted considerable interest for its potential in clinical translation." (PMID 41567188, 2025). "CD8+ T cells execute tumor killing via perforin/Granzyme-B, whereas Th1-polarized CD4+ cells amplify cytotoxicity through IFN-γ and IL-2." (PMID 41300366, 2025). "CD103 is then recruited into the immune synapse where it promotes exocytosis of oncolytic granules containing perforin and granzyme B, which leads to the lysis of tumor cells." (PMID 41194931, 2025). "CD8+ TILs, in particular, are the primary effector cells responsible for cytotoxicity, capable of killing tumor cells through the secretion of perforin, granzyme B, and IFN-γ." (PMID 40444078, 2025). "Levels of cytotoxic proteins, including STAT1, TNF-α, GZMB, and Perforin in tumor tissues were sharply enhanced by sh-TBX21 injection." (PMID 41573646, 2025). "Our results demonstrated significant functional impairment in NK cells, characterized by decreased secretion of cytotoxic molecules (perforin, granzyme B, and CD107a) and diminished tumor-killing capacity." (PMID 40231264, 2025). "In ex vivo analyses, increased numbers of AH1-specific T cells were observed relative to intra-tumoral CD8 T cells, as well as elevated granzyme B expression in these tumor antigen-specific cells, which correlated with a reduction in tumor mass." (PMID 40315226, 2025). "As SERPINB9 protects cells from granzyme B induced apoptosis, its reduced functionality in macrophage-like cells, which are primarily found in the tumor core, can lead to increased apoptosis and hence a reduced immune response." (PMID 39936571, 2025). "A basic understanding of granzyme B relates to its anti-tumor function, given at least the fact that CTLs have been shown to directly kill tumor cells via the perforin/granzyme pathway." (PMID 40766321, 2025). "Subsequently, after restaining, dehydration, and mounting, images were captured under a microscope, and the expression of CD8 and Granzyme B in the tumor tissues of each group was analyzed using ImageJ software." (PMID 40430847, 2025).
tumor (continued). "On the contrary, it was negatively correlated with cytokine‐encoding related genes such as IFNG, GZMB, PRF1, and TNF in most tumor types." (PMID 40013761, 2025). "Gastric-cancer spheroid assays demonstrate that nightly (but not daytime) melatonin pulses synchronise T-cell NAD+ oscillations, sharpen granzyme-B release and restrain tumour growth—an effect abrogated in BMAL1-knockout mice." (PMID 40791587, 2025). "They found that the best predictors of immunotherapy response are the proliferating CD8+TCF1+ T cells and MHC-II+ tumor cells, followed by B cells and granzyme B+ T cells." (PMID 41425696, 2025). "This review highlights the distinct yet potentially complementary roles of GZMB and melittin in modulating tumor cell death and the tumor microenvironment." (PMID 40766321, 2025). "Immunofluorescence staining of the tumor sections for CD8a and granzyme B (GZMB) revealed that codelivered immunomodulatory agents (iBINP) elicited a potent cytotoxic CD8+ T cell response." (PMID 41129257, 2025). "Mechanistically, CD8+ T cells secret large amounts of IFN-γ and the protease granzyme B, which act synergistically to kill infected or tumor cells." (PMID 38778609, 2025). "Some of these enzymes can induce tumor cell death, such as ribonuclease A (RNase A), cytochrome C (Cyt C), and granzyme B (GrB)." (PMID 40565310, 2025). "Tc cells are essential markers of the anti-tumor immune response, inducing apoptosis of target cells via cytotoxin release (such as perforin and granzyme B) and producing pro-inflammatory cytokines, like IFN-γ and TNF-α." (PMID 40136347, 2025). "In pathological samples from nasopharyngeal carcinoma patients, numerous GZMB+ tumor-infiltrating lymphocytes (TILs) were identified." (PMID 41567188, 2025). "Regarding their functionality, CD8+ T cells exert their effects on tumor cells through the elevated expression of perforin, granzyme B, IFN-γ, and TNF-α." (PMID 38778609, 2025). "They induce tumor cell apoptosis via the Fas/FasL pathway and inhibit metastatic niche formation through the secretion of Granzyme B." (PMID 40964092, 2025). "Exosomes derived from mesothelin (MSLN)‐targeted CAR‐T cells have been shown to effectively target MSLN‐positive TNBC cells and inhibit tumour growth by secreting perforin and granzyme B." (PMID 40032646, 2025). "For instance, lactate can bind to GPR132 on natural killer (NK) cells, suppressing the expression of interferon-γ (IFN-γ) and granzyme B (GZMB), thereby facilitating tumor progression." (PMID 41152975, 2025). "Ex vivo expanded human ILC2s (Ex ILC2s) can kill tumor cells through the secretion of GzmB, mediated by the DNAM-1–CD112/CD155 receptor-ligand interaction." (PMID 40963622, 2025). "PD-1 signaling is conventionally recognized to suppress IFN-γ, TNF-α, Perforin, and Granzyme B in tumor-infiltrating T cells." (PMID 40825269, 2025). "Through death ligands or the perforin/granzyme B pathways, activated CTLs effectively induce apoptosis in tumour cells." (PMID 40830825, 2025). "In our study, a reduction in the transcription of GZMB in the macrophages and DC in the tumours of BH-treated subjects compared to the sham-exposed controls was seen." (PMID 40870972, 2025). "Macrophages exposed to SAA curtailed the expansion of CD8+ T cells and the generation of Granzyme B–expressing effector T cells, resulting in significantly impaired tumor cell killing." (PMID 41488634, 2025). "T cells within tumor-enriched neighborhoods presented increased expression of effector and exhaustion markers such as PD-1, Granzyme B, and ICOS, whereas those in stromal-enriched neighborhoods presented reduced activation marker expression." (PMID 41254766, 2025). "This inhibition is comparable to the effect of the mechanistic target of rapamycin complex 1 (mTORC1) inhibitor rapamycin, as both TGF-β and rapamycin reduce NK cell proliferation, granzyme B expression and cytotoxicity against tumour cells." (PMID 41429765, 2025).
tumor (continued). "The treatment of mice with anti–PD-L1 combined with bacteria provided analogous control of tumor growth as the combination of the antibody with apyrase as well as a similar increase in TNF-α+Granzyme B+ and CXCR5+ CD8 TILs." (PMID 41042869, 2025). "Granzyme B (GZMB) secreted by human ILC2s directly lysed tumour cells by inducing pyroptosis and/or apoptosis." (PMID 40801800, 2025). "In co-culture assays, it enhanced T cell-dependent tumor killing and restored the expression of key cytokines (GZMB, IFN-γ, IL-2, TNF-α) suppressed by tumor-derived immunosuppression." (PMID 41373467, 2025). "Upon antigen recognition, TRM cells rapidly reactivate through TCR–pMHC signaling, triggering MAPK/ERK and NF-κB pathways and releasing effector molecules such as IFN-γ and granzyme B, thereby exerting direct cytotoxicity against tumor cells." (PMID 41458510, 2025). "Previous studies have documented GZMB’s anti-tumor effects through classical mechanisms, highlighting its significance in tumor immunity." (PMID 41567188, 2025). "These cells exhibit elevated expression of cytolytic effector molecules, such as PRF1 and GZMB, supporting their role in persistent tumor surveillance." (PMID 40859981, 2025). "In the lung tissues, the triple treatment group was the only group showing a significant increase of Granzyme B, a critical component of the cytotoxic T cell response, suggestive of an enhanced anti-tumor immunity in lungs." (PMID 40104170, 2025). "A reduction in Granzyme B, a serine protease mainly secreted by NK and cytotoxic T cells and involved in anti-tumor T cell response, was also highlighted." (PMID 40725070, 2025). "The combination treatment inhibited the EGFR/JAK/STAT3 signaling pathway and reduced PD-L1 expression, concurrent with increased immune-mediated tumor cell death through the perforin/granzyme B pathway." (PMID 40347254, 2025). "The elevated granzyme B expression and T-cell infiltration indicate an activated immune response and tumor cell cotoxic." (PMID 40595481, 2025). "It shows increased tumor-infiltrating CD8+ T cells, enhanced cytokine production (IFN-γ, granzyme B), tumor rejection, and immunological memory in mice." (PMID 41155952, 2025). "We observed a higher number of Granzyme B+ cells in both the border and the central areas of the tumor from MSLN nanovaccinated mice compared to mice that received the NP control." (PMID 40266223, 2025). "For Triple‐I tumors, in addition to IFNG mediated cytotoxic T‐cell tumor killing involving genes, like GZMB, high AIM2 along with NLRP1 expression support a role of pyroptosis via inflammasomes." (PMID 40492347, 2025). "This is further supported by our data showing that coculturing PSCA CAR_sIL-15 iNKT cells with either gemcitabine-sensitive or GR PSCA+ tumor cells boosts secretion of granzyme B, IFN-γ, and TNF-α when compared with control sIL-15 iNKT cells." (PMID 40231459, 2025). "Previous studies have shown that activation of NK cell increase the synthesis and release of Perforin and Granzyme B, thereby enhancing their ability to kill tumor cells." (PMID 41357886, 2025). "Previous research has consistently shown that B cell-derived GZMB plays a pivotal role in anti-tumor activity, with patients exhibiting a higher proportion of GZMB+ B cells demonstrating improved prognoses." (PMID 41567188, 2025). "They observed that NK cells in animals treated with hypoxic tumor-derived microvesicles displayed decreased levels of CD107a, IFNγ, and GZMB compared with NK cells from animals treated with normoxic tumor-derived microvesicles." (PMID 41227342, 2025). "In vivo therapeutic experiments showed a significant increase in granzyme B levels within tumours and strengthened the cytotoxic activity of CD8+ T cells, thereby augmenting the anti‐tumour effect." (PMID 40665579, 2025). "In particular, IFN-responsive cancer cells, GzmB+ cytotoxic T cells, as well as C1q macrophages, increase in parallel with tumor progression." (PMID 41280683, 2025).
tumor (continued). "Consistently, Allo15CAR33-NKT cells displayed increased production of cytotoxic molecules, such as Granzyme B, when targeting Decitabine-treated tumor cells." (PMID 39893165, 2025). "Significant differences in the NK subsets were confined to the cNK cells, which exhibited a significant increase in both single granzyme B expression and perforin A/granzyme B double-positivity in the tumor-infiltrating cells compared to those in the liver." (PMID 41268557, 2025). "In blood, before PD-1 blockade, tumor-TCR-matched CD4+ cells were predominantly GZMB+ in pre-atezolizumab blood (average 35%–37% of branches A and B), with a minority of GZMK+ (2.8%–5.2% of branches A and B)." (PMID 40299576, 2025). "Again, PP2A-deficient CD8+ T cells exhibited reduced tumor infiltration and fewer cells expressed IFN-γ, TNF-α, and GZMB." (PMID 39759159, 2025). "Downregulated were the critical genes CAV1, VWF, and DCN, suggesting loss of tumour-suppressive functions, and upregulated were SCGB2A1, CLDN4, and immune-related genes CCL3 and GZMB, promoting tumour growth and immune evasion." (PMID 41312167, 2025). "Our study revealed that iEV-150 significantly increased CD8+ T-cell infiltration and granzyme B expression in tumor-bearing mice, suggesting improved antitumor immunity." (PMID 40860143, 2025). "GZMB+ pDCs suppress T-cell proliferation through a perforin-independent mechanism, thereby significantly contributing to tumor immune evasion." (PMID 41567188, 2025). "Techniques such as quantitative real-time polymerase chain reaction, western blotting and immunohistochemistry have shown that GZMB mRNA and protein levels are significantly elevated in GC tissues, correlating with tumor progression." (PMID 40766321, 2025). "After treatment with αNKG2A-N215, both tumor-infiltrated granzyme B- and CD25-expressing CD8+ T and NK cells were drastically increased, indicating that αNKG2A-N215 orchestrated both CD8+ T and NK cells to combat tumors." (PMID 40170468, 2025). "Cells in the DC-C3 cluster, uniquely express GZMB, and along with neutrophils, were increased in MI basal tumour samples." (PMID 41281745, 2025). "Overall, our results demonstrate that CAR-CLDN18.2 γδ T cells can effectively recognize CLDN18.2-positive target tumor cells and secrete high levels of Granzyme-B, Perforin-1, and IFN-γ to exert antitumor effects." (PMID 40149332, 2025). "The γδ T lymphocytes exert their cytotoxic activity against tumor cells through multiple mechanisms, including the secretion of perforin and granzyme B, as well as the Fas/FasL pathway." (PMID 40136347, 2025). "Analysis of GzmB expression revealed that TRM-like cells comprised the majority of GzmB+ CD8+ T cells across all time points but their relative frequency diminished as the tumor progressed." (PMID 41279375, 2025). "Consistent with this, IHC staining for GzmB revealed elevated GzmB+ cell numbers in propionate-treated tumours, which were significantly reduced upon Meox1 knockdown." (PMID 40715695, 2025). "The findings revealed that in comparison to peripheral blood PBMCs, the secretion of IFN-γ and GZMB by CD8+ T cells was notably diminished in tumor tissues." (PMID 40040705, 2025). "They secrete anti-tumor cytokines (IFN-γ and TNF-α), and cytotoxic molecules such as perforin and granzyme-B, effectively killing HLA-null tumor cell lines like K562 cells." (PMID 40110110, 2025). "CODEX multiplexed IF showed that Takinib-treated tumors had increased total and proliferating CD4+ and CD8+ T cells, as well as granzyme B-expressing CD8+ T cells that were physically closer to tumor cells." (PMID 41280086, 2025). "GZMB, as a member of the granzyme family, enters the interior of tumor cells to activate apoptotic pathways, directly leading to the death of tumor cells." (PMID 41573646, 2025). "In parallel, STING signaling in NK cells themselves enhances the release of cytolytic mediators, including perforin and granzyme B, thereby potentiating their tumor-killing capacity." (PMID 41239499, 2025).